GZMB (granzyme B)
Diseases named in the same sentence as GZMB in open-access papers (continued):
Sharing a sentence is not in itself a finding about the gene and the disease.
psoriasis (14 papers, 2020 to 2025). An autoimmune condition characterized by red, well-delineated plaques with silvery scales that are usually on the extensor surfaces and scalp. "Granzyme B, a serine protease, plays a significant role in autoimmune skin disorders such as psoriasis and AA." (PMID 39859462, 2025). "Granzyme B inhibition and autophagy restoration represent promising therapeutic approaches for managing psoriasis and AA." (PMID 39859462, 2025). "In psoriasis, granzyme B drives keratinocyte hyperproliferation and inflammation, whereas in AA, it facilitates autoimmune-mediated follicular destruction." (PMID 39859462, 2025). "In psoriasis, granzyme B contributes to the inflammatory processes and the proliferation of skin cells, exacerbating the disease’s characteristic symptoms such as scaling and redness." (PMID 39859462, 2025). "As the expression level of GZMB increases, the SHAP value gradually increases, indicating that the high expression of GZMB in CD8+ T cells drives the pathogenesis of psoriasis." (PMID 38915827, 2024). "Similarly, upon PMA/ION stimulation, CD8+CD45RA-CD45RO- T cells expressing Granzyme B (Cluster 17) were downregulated in psoriasis patients compared to healthy volunteers (left)." (PMID 40391222, 2025). "Studies have shown that the expression of GZMB is elevated in skin lesions and plasma of psoriasis patients, suggesting that GzmB may be involved in CD8+ T cell-mediated cell damage and inflammation." (PMID 38915827, 2024). "We identified GZMB, GNAS, GBP5, FOXP3, LSP1 and CD81 as characteristic genes of psoriasis-associated CD8+ T cells, among which, Granzyme B (GzmB), a serine protease, is produced by natural killer (NK) cells and CD8+ T cells, and is an vital mediator of skin injury, inflammation and repair." (PMID 38915827, 2024). "At present, the role of GzmB in psoriasis pathophysiology is poorly understood." (PMID 36830757, 2023). "Our observation of elevated GzmB+ CD49a+ Trm in lesions of resolved psoriasis suggests that these cells may play an important function in the in situ activation of epidermal T cells." (PMID 33007963, 2020). "For example, the use of GZMB knockout CAR-T cells in patients may delay psoriasis progression." (PMID 38915827, 2024). "Our analysis identified CASP1, CASP5, AIM2, NOD2, GZMB, GZMA, and IL1B as key hub genes in the inflammatory pathways driving psoriasis pathogenesis." (PMID 40771724, 2025). "We observed reduced functionality of peripheral blood CD8 T cells from psoriasis patients compared to healthy control, with a significant decrease in CD69, Granzyme B and IFNγ expression across CD8 T cell subsets following TCR-dependent stimulation." (PMID 40391222, 2025). "Total memory, central memory, effector memory, and naïve CD8 T cell subpopulations from psoriasis patients exhibited a significantly lower percentage of CD69+, Granzyme B+, and IFNγ+ cells compared to healthy controls when stimulated with anti-CD3/CD28." (PMID 40391222, 2025). "The frequency of CD69+, Granzyme B+ and IFNγ+ CD8 T cells in psoriasis patients was significantly lower following anti-CD3/CD28 stimulation (p<0.0005), suggesting downregulated TCR-dependent activation and impaired Tc1 cytokine production in CD8 T cells from psoriasis patients." (PMID 40391222, 2025). "Higher numbers of PRF1 and GZMB positive cells were detected by immunohistochemistry in lesional skin of AD- and psoriasis patients when compared to non-lesional or healthy skin of respective patients." (PMID 37470818, 2023). "Finally, the qRT-PCR results demonstrated the apparent dysregulation of PRGs in psoriasis, especially AIM2 and GZMB." (PMID 36110207, 2022). "Notably, GZMB and CASP1 occupied central positions within the network, each displaying multiple direct links with other PRGs, suggesting potential roles as core regulators of pyroptotic signaling in psoriasis." (PMID 40771724, 2025).
tuberculosis (14 papers, 2017 to 2025). A chronic, recurrent infection caused by the bacterium Mycobacterium tuberculosis. "Human CD8+ cytotoxic T cells expressing the cytotoxic granule proteins granzyme B, perforin, and granulysin have been linked to host defense in leprosy and tuberculosis, with both granulysin and granzyme B having direct antimycobacterial activity." (PMID 40569678, 2025). "Sustained expression of granzyme B and PD-1 was also observed during tuberculosis (TB) and HIV-1/TB co-infection." (PMID 34951583, 2021). "PD-1 blockade is described to increase perforin, granzyme B, and granulysin expression in T-cells of tuberculosis and cancer patients." (PMID 29312350, 2017). "However, Granzyme B levels increased steadily from baseline to treatment completion suggesting a possible role in host immune response to tuberculosis." (PMID 40547033, 2025). "Specifically, the natural killer cell subsets (CD3-CD7+GZMB+) are gradually depleted from HC to LTBI and TB, and it is proved that the change in the frequency of this subset can distinguish tuberculosis patients from latent patients and healthy people." (PMID 37901241, 2023). "In conclusion, high Granzyme-B+PD-1+ T cell responses to M. tuberculosis and, possibly, of CD8+GMM+Granzyme-B+ T cells may be desirable for new TB vaccines." (PMID 37564701, 2023). "In a recent study, scRNA‐seq analysis of peripheral blood mononuclear cells (PBMCs) from healthy controls (HCs), latent tuberculosis infection (LTBI) and active tuberculosis (TB) revealed a subset characterized by CD3−CD7+GZMB+ NK cells not reported before." (PMID 35906816, 2022). "Analysis of the validation set data revealed reduced levels of GZMB and PRF1 in latent tuberculosis infection (LTBI) and TB patients compared to those in HI, alongside significantly elevated expression levels of the LAG-3 and IFN-γ genes in these samples." (PMID 38957797, 2024).
acute myeloid leukemia (13 papers, 2012 to 2026). Acute myeloid leukemia (AML) is a group of neoplasms arising from precursor cells committed to the myeloid cell-line differentiation. "In acute myeloid leukemia, elevated TIM-3 expression on NK cells correlates positively with perforin and granzyme B levels and is associated with improved clinical outcomes." (PMID 41544143, 2026). "Interestingly, ICP+ Vγ9Vδ2 T cells maintain the ability to produce IFNγ and to secrete GzmB and Prf in MM, acute myeloid leukemia (AML), and other cancers." (PMID 37143664, 2023). "BPDCN is usually positive for CD56, but negative for granzyme B, whereas in the cutaneous accumulation of plasmacytoid dendritic cells associated with acute myeloid leukemia, the results are the opposite." (PMID 25621057, 2015). "In a model of acute myeloid leukemia (AML) only wild-type Tregs prevented tumor rejection, compared to Granzyme B knockout (Gzmb−/−) or Perforin1 knockout (Prf1−/−) Tregs." (PMID 29032503, 2018). "In acute myeloid leukemia, membrane HSP70 can be specifically recognized by NK cells via CD94/CD56 to produce granzyme B (GZMB) for cytolytic activity." (PMID 33023034, 2020). "Interestingly, exposure of acute myeloid leukemia (AML) cells to this same TPOR agonist antibody promoted their differentiation into natural killer (NK)-like AML cells that synthesized large amounts of perforin, granzyme B and interferon-γ, and thereby induced apoptosis in undifferentiated AML." (PMID 33923551, 2021).
breast tumor (12 papers, 2003 to 2025). "This process is affected by the activity of granzyme B, but at the same time FGF10 shows a positive regulatory effect on granzyme B, which ultimately leads to the enhancement of breast tumor invasion and migration ability." (PMID 35668376, 2022). "It has been documented that, through TRAIL and Granzyme B, the activated pDC can kill breast tumor cells." (PMID 33869191, 2021). "Accordingly, we further used preclinical TNBC models to demonstrate that intratumoral S. aureus, the predominant Staphylococcus species in human breast tumors, enhanced the expression of granzyme B in CD8+ TILs, thereby inhibiting tumor growth in a CD8+ cell-dependent manner." (PMID 39554133, 2024). "When evaluating all genes available in TCGA (N = 20,530) the gene expression differences between immune-high and low breast tumors included immune response genes including T cell signaling (e.g., IL2RG) and function (e.g., GZMB)." (PMID 39149486, 2024). "Activated pDCs directly destroyed breast tumor cells in vitro in a TRAIL and Granzyme B-dependent fashion." (PMID 28052019, 2017). "Activated pDCs can directly kill breast tumor cells in a TRAIL and Granzyme B-dependent fashion." (PMID 28052019, 2017). "Finally, lower levels of several pro-inflammatory cytokines (IL1B, IL10, IL12, IL6, IL8, TNF), NK cell metagenes (NCR1, XCL1), cytolytic enzymes (GZMA, GZMB, PRF) and type I IFN-induced genes were also observed in IL-1R8 high breast tumors." (PMID 28533483, 2017).
leishmaniasis (12 papers, 2014 to 2025). Infectious disease that is transmitted through the bite of hematophagous female phlebotomine sand flies. "On the other hand, NK cells may also play a role in the immunopathology of leishmaniasis, mainly due to the release of granzyme B, which enhances the cytotoxicity found in cutaneous leishmaniasis patients." (PMID 39963187, 2025). "Very few reports have investigated the involvement of granzyme B in human leishmaniasis." (PMID 24786587, 2014). "Parasite-specific granzyme B production by human peripheral blood mononuclear cells (PBMCs) was found to be a good correlate of protection against Leishmania infection and could be a biomarker of vaccine-induced protection against human leishmaniasis." (PMID 35419001, 2022). "Interestingly, VL patients also exhibit higher expression of GZMA, GZMB, and PRF1 in the blood compared to healthy subjects, indicating a potential common cytolytic response in leishmaniasis." (PMID 33793565, 2021). "The significant recognition of LACK by the T receptors of the present cured and asymptomatic subjects, plus the ability of this protein to induce IFN-γ, TNF-α, and granzyme B (CD4+ and CD8+ T cell responses), indicates this antigen to be of potential use in vaccines against human leishmaniasis." (PMID 29740446, 2018). "Interestingly, this T-cell dysfunction was observed months after the initiation of the Leishmaniasis treatment, despite the increase of costimulatory molecules after SLA stimulation, and it resulted in low IFN-γ in CD8+ and CD4+ and granzyme B on CD8+." (PMID 29867989, 2018). "The production of IFN-γ, TNF-α, granzyme B, IL-5 and IL-10 by SLA-stimulated PBMCs, and of IFN-γ, TNF-α and IL-2 by SLA-stimulated whole blood, could be used to indicate exposure to leishmaniasis, especially for patients subjected to induced immunosuppression." (PMID 26496365, 2015). "In addition, while the subjects cured of leishmaniasis exhibited monofunctional cells that individually expressed all the analyzed molecules, CD8+ T cells from patients with active CL preferentially expressed granzyme B or IL-2." (PMID 30510917, 2018).
bladder cancer (11 papers, 2016 to 2025). "The researchers further assessed its function using bladder cancer cell lines and found that tumor-derived GZMB possesses enzymatic activity capable of cleaving fibronectin and remodeling the ECM." (PMID 41567188, 2025). "TRMs isolated from bladder cancer patients proliferate and upregulate T-bet, perforin, and granzyme B in response to IL-15 stimulation." (PMID 41479900, 2025). "Mitazalimab prolonged survival of mice bearing MB49 bladder carcinoma tumors and increased the frequency of activated granzyme B+ CD8+ T cells in the tumor." (PMID 33948686, 2021). "In bladder cancer, TRMs can be activated by anti-CD3, anti-CD28, and IL-15 stimulation, leading to proliferation and increased T-bet, perforin, and granzyme B expression, particularly in the PD-1+ subset." (PMID 41479900, 2025). "Notably, PDLIM2 expression was strongly correlated with TIM-3 in bladder cancer and with PDCD1, CTLA4, GZMB, and LAG3 in KIRP." (PMID 35121770, 2022).
co-infection (11 papers, 2016 to 2025). "CMV co‐infection was associated with a robust, 36‐fold expansion of GzmB+Perforin+ CD4+ T cells among EBV/HSV‐seropositive individuals, with comparable frequencies observed in both RA patients and controls." (PMID 41235706, 2025). "SIV co-infection and CD4 depletion also changed the overall composition of T cells within lung granulomas that produce these cytokines and granzyme B." (PMID 32730321, 2020). "Granulysin may act synergistically with perforin and IFN-γ by the significant correlation of granulysin with granzyme-B and perforin levels in TB or HIV/TB coinfection, and their effector mechanisms could contribute to control TB." (PMID 32823923, 2020). "Before anti-TB treatment, the in vitro levels of granulysin, perforin, granzyme-B and IFN-γ released from PBMCs of active TB or HIV/TB coinfection patients after PPD and H37Ra stimulation were analyzed in comparison with those of HIV+HAART−, HIV+HAART+ and healthy individuals (HC) as controls." (PMID 32823923, 2020). "Upon stimulation, the non-significantly higher median levels in TB than HIV/TB coinfection were observed in granulysin, perforin and granzyme-B." (PMID 32823923, 2020).
colitis (11 papers, 2017 to 2026). Inflammation of the colon. "Indeed, CD4 CTLs are critically involved in the induction of colitis since colitis induction is reduced in granzyme B-deficient mice." (PMID 28280496, 2017). "Here, we focused on the use of positron emission tomography directed towards granzyme B, a serine protease released by activated cytotoxic T cells and natural killer cells, to evaluate the dynamics of therapeutic response in a colitis model." (PMID 42196181, 2026). "In LPMCs from mice with CPI colitis there was significantly increased production of IFNγ and granzyme B in comparison to control mice." (PMID 37872166, 2023). "Activated CD8+ T cells express cytotoxic molecules such as perforin and granzyme B that can damage the intestinal epithelium and aggravate colitis." (PMID 29419930, 2018). "The goal was to explore the use of granzyme B positron emission tomography as a non-invasive biomarker to monitor disease activity and therapeutic response across several treatments in a dextran sulfate sodium-induced colitis model." (PMID 42196181, 2026). "The data demonstrate that epithelial STAT1 is required for colitis‐associated intraepithelial infiltration of CD8+ TCRαβ+ granzyme B+ T cells in male but not in female mice." (PMID 29419930, 2018). "Therefore, reduced numbers of intraepithelial CD8+ TCRαβ+ granzyme B+ T cells during DSS‐induced colitis might have created an immune‐privileged microenvironment in male STAT1∆IEC mice that led to a higher tumor load despite of reduced colitis." (PMID 29419930, 2018). "The increase of intestinal inflammation in Tlr7-/- mice correlated with an increase in granzyme B+ CD8+ TRM cells, IFN-γ, and TNF-α secretion during DSS colitis and suggest that CD8+ TRM cells contribute to the increased susceptibility seen in Tlr7-/- mice." (PMID 39464882, 2024). "We identified polyfunctional mucosal CD4+ and CD8+ T cells that co-produce IFNγ, other pro-inflammatory cytokines (e.g. IL22, IL17A) and cytotoxic molecules, including granzyme B, as key effector cells in CPI colitis." (PMID 37872166, 2023). "An increased proportion of colonic T cells co-expressing IFNγ granzyme B and perforin was observed in CPI colitis, especially in CD4+ and CD8+ T cells." (PMID 37872166, 2023). "In agreement with our findings, we observed increased expression of IFNG, GZMB CXCR6 and CTLA4 in T cell clusters in with patients with CPI colitis patients in comparison with healthy controls." (PMID 37872166, 2023). "Male but not female STAT1∆IEC mice were more resistant to DSS‐induced colitis than sex‐matched controls and displayed reduced intraepithelial infiltration of CD8+ TCRαβ+ granzyme B+ T cells." (PMID 29419930, 2018). "Concomitant with attenuated colitis, intraepithelial infiltration of CD8+ TCRαβ+ granzyme B+ T cells was reduced in male STAT1∆IEC mice." (PMID 29419930, 2018). "Reduced intraepithelial granzyme B+‐cell infiltration during DSS‐induced colitis was preserved in AOM‐DSS‐induced tumors of male STAT1∆IEC mice, which contained lower numbers of granzyme B+ cells than sex‐matched control tumors." (PMID 29419930, 2018). "Male but not female STAT1∆IEC mice were more resistant to DSS‐induced colitis than sex‐matched STAT1flox/flox controls and displayed reduced intraepithelial infiltration of CD8+ TCRαβ+ granzyme B+ T cells." (PMID 29419930, 2018). "In this case, the increased expression of granzyme B and perforin in CD8+ cells would result in a highly cytotoxic profile of these cells in USP28-/- mice, which would be consistent with the exacerbated symptoms seen in acute DSS colitis." (PMID 39076972, 2024).
emphysema (11 papers, 2007 to 2025). "The pathogenic mechanisms responsible for the production of emphysema act in several ways: CD8+ T lymphocytes secrete proteases such as Granzyme B, which lead to the degradation of the extracellular matrix." (PMID 39851472, 2025). "In addition, CD8 cells can release perforin, granzyme B, causing cell lysis and apoptosis of alveolar epithelial cells, thereby promoting the development of emphysema." (PMID 38076255, 2023). "These cells also release perforin and granzyme B, inducing lysis and apoptosis of alveolar epithelial cells and advancing emphysema development." (PMID 40386214, 2025). "Some studies have reported that NK cells can secrete cytotoxic mediators, such as granzyme B and perforin, which may play an important role in inducing lung cell apoptosis and thereby promoting emphysema." (PMID 35350787, 2022). "Regarding the specific role of NK cells in COPD, some authors have reported that their cytotoxic mediators (i.e., granzyme B and perforin) may be involved in inducing apoptosis in the lungs, thus facilitating emphysema." (PMID 32131843, 2020). "Upregulation of granzyme B in CD8+ and non-CD8+ cells has been demonstrated to be an early phenomenon of small airway wall remodelling in centrilobular emphysema in patients with COPD." (PMID 25848680, 2015). "This study was designed to determine if, in the presence of systemic inflammation, the expression of the cytotoxic and activation markers, perforin, granzyme B, and FasL, by peripheral CD8+ T lymphocytes was upregulated in emphysema." (PMID 17822550, 2007). "For example, it would be of particular interest to extend previous observations supporting a role for granzyme B in the pathogenesis of emphysema by defining which cell types harvested by BAL from area of radiographically-confirmed emphysema express that cytotoxic molecule." (PMID 25622723, 2015).